NLRP3 (NLR family pyrin domain containing 3)
Diseases named in the same sentence as NLRP3 in open-access papers (continued):
Sharing a sentence is not in itself a finding about the gene and the disease.
Insulin resistance (continued). "Inflammatory responses, such as NLRP3 inflammasome, play a critical role in the pathogenesis of insulin resistance." (PMID 30761259, 2019). "Endotoxemia (i.e., LPS in the blood) resulting from barrier dysfunction activates the NLRP3 inflammasome and results in mitochondrial dysfunction and IL-1b production and insulin resistance with important consequences for neuronal function." (PMID 31920905, 2019). "We also demonstrate that Kir6.1 controls insulin resistance by inhibiting NLRP3 inflammasome activation in mice." (PMID 31387986, 2019). "In contrast, the monounsaturated OA impaired adipose NLRP3 inflammasome-mediated IL-1β secretion and insulin resistance via the preservation of AMPK activity in animal and in vitro models." (PMID 31817726, 2019). "Our results reveal a previously unrecognized function of Kir6.1 as a negative regulator of the NLRP3 inflammasome and insulin resistance, which is mediated by virtue of its ability to inhibit NLRP3 inflammasome assembly." (PMID 31387986, 2019). "The objective of this study was to explore the possible function of the K+ channel pore-forming subunit Kir6.1 in regulating NLRP3 inflammasome activation and insulin resistance." (PMID 31387986, 2019). "In conclusion, our study reveals a previously unrecognized function for Kir6.1 as a negative regulator of the NLRP3 inflammasome and insulin resistance." (PMID 31387986, 2019). "The NLRP3 inflammasome plays a critical role in the progression of insulin resistance during the course of T2DM, but its role in the autoimmune T1DM remains to be investigated." (PMID 31835423, 2019). "The influential role of NLRP3 in insulin resistance has been studied in animal models and human adipose tissue samples." (PMID 31835423, 2019). "Activation of NLRP3 and subsequent IL-1β production are the single greatest factors that drive insulin resistance, and NLRP3 KO mice are protected from developing insulin resistance." (PMID 31920905, 2019). "Specifically, LPS-TLR activation of the NLRP3 inflammasome induces production of IL-1β resulting in insulin resistance, mitochondrial dysfunction, and ROS production, further NLRP3 activation and neuroinflammation and neurodegeneration." (PMID 31920905, 2019). "Numerous researches have showed that the activation of NLRP3 inflammasome and the release of downstream IL-1β and IL-18 can promote the process of liver inflammation, triglyceride deposition, and insulin resistance during the NAFLD/NASH." (PMID 31827504, 2019). "This association between metabolic stress and inflammation suggests a link between inflammasome activation, especially the activation of NLRP3, and insulin resistance." (PMID 31197747, 2019). "Previous studies have proved the connection between the activation of the NLRP3 inflammasome and insulin resistance." (PMID 31558153, 2019). "We reveal a previously unappreciated function of Kir6.1 as a negative regulator in the activation of the NLRP3 inflammasome and the development of insulin resistance in vivo and in vitro." (PMID 31387986, 2019). "Previous studies have shown that inflammation is a key contributor to insulin resistance and T2D, and the NLRP3 inflammasome plays a critical role in the development of insulin resistance in T2D14–16." (PMID 30291237, 2018). "To date, only one study has shown that gavage of DHA in high-fat diet-fed mice attenuated NLRP3 inflammasome activation and prevented mice from high-fat diet-induced insulin resistance at a whole-body level." (PMID 28729463, 2017). "Taken together, these results demonstrate that NLRP3 impaired the normal insulin signaling pathway and led to insulin resistance; IL-1β, a downstream molecular of NLRP3, also played a key role in regulating insulin sensitivity." (PMID 29096724, 2017). "PA, one of the most abundant SFAs in the modern diet induces activation of the NLRP3 inflammasome in hematopoietic cells, which results in insulin resistance and glucose intolerance in mice." (PMID 29258239, 2017).
Insulin resistance (continued). "In this study, we confirmed in vitro that the NLRP3 inflammasome was activated in an LPS and palmitic acid (PA)-induced inflammation model of insulin resistance in HepG2 cells." (PMID 29096724, 2017). "MSCs effectively inhibit NLRP3 inflammasome activation and decrease these inflammatory cytokines, contributing to the amelioration of insulin resistance." (PMID 29096724, 2017). "Nod-like receptor family pyrin domain containing 3 (NLRP3) contributes to obesity-induced inflammation and insulin resistance." (PMID 29164155, 2017). "Activation of IL-1β, mainly through cleavage by the NLRP3 inflammasome, promotes insulin resistance." (PMID 29435463, 2017). "Together these data indicated that the NLRP3 inflammasome-sensing pathway contributes to inflammation in insulin resistance." (PMID 29096724, 2017). "Our study showed that WMW inhibited IL-1β production and relieved insulin resistance in palmitate-treated HepG2 cells via reduction of the expression of the three components of NLRP3 inflammasome: NLRP3, ASC, and caspase-1 (p20)." (PMID 28928791, 2017). "Our previous studies have indicated that mitochondrial Rho (Miro) GTPase-mediated mitochondrial dysfunction under high nutrient stress leads to NOD-like receptor 3 (NLRP3)-dependent proinflammatory responses and subsequent insulin resistance." (PMID 29207597, 2017). "Mice with reduced expression of NLRP3 are protected from diet-induced insulin resistance, correlating with the reduced activation of T cells in adipose tissue." (PMID 27321128, 2016). "Despite a low myotoxic profile, fluvastatin has been reported to activate the NLRP3 inflammasome and induce adipose tissue insulin resistance in obese animals at levels comparable to, or greater than lovastatin, atorvastatin, and simvastatin." (PMID 27486434, 2016). "Glyburide is also an inhibitor of the Nlrp3 inflammasome, an attractive target for metabolic-inflammation, given the detrimental effect it has in both inflammation and insulin resistance." (PMID 27128935, 2016). "The IPGTT revealed that the reduced expression of PDE3B and NLRP3 inflammasome led to substantial protection against HFD-induced insulin resistance." (PMID 27321128, 2016). "The key role of the Nlrp3 inflammasome as central mediator in the inflammatory response to tissue injury during either myocardial infarction or insulin resistance is already known." (PMID 26788246, 2016). "It was also found that ceramides induced the NLRP-3 inflammasome, driving the secretion of IL-1β followed by the development of insulin resistance." (PMID 26788518, 2016). "In recent years, the nucleotide-binding domain and leucine-rich-repeat and pyrin domain containing 3 (NLRP-3) inflammasome has been identified as a major contributor to the development of systemic inflammation and insulin resistance." (PMID 26788518, 2016). "NLRP3 inflammasome has been suggested as a link between insulin resistance, obesity, circulating immune markers, immunogenetic susceptibility, macrophage function, and chronic inflammation." (PMID 26273672, 2015). "The NLRP3 inflammasome is a multi-protein complex which instigates the inflammatory response and contributes to insulin resistance." (PMID 26355342, 2015). "Accumulating evidence supports the idea that the NLRP3 inflammasome has a critical role in the development of adipose tissue inflammation and insulin resistance." (PMID 24064574, 2013). "Most recent data suggest that activation of the NLRP3 inflammasome complex contributes to the pathophysiological mechanisms that explain the development of visceral obesity and insulin resistance." (PMID 23843683, 2013). "This is critical given the bidirectional relationship between oxidative stress and inflammation in MetS pathogenesis: ROS activate NF-κB and NLRP3 inflammasomes, driving cytokine production that further exacerbates insulin resistance and endothelial dysfunction." (PMID 41596333, 2026).
Insulin resistance (continued). "In PCOS, persistent metabolic stressors, such as insulin resistance, hyperinsulinemia, and elevated androgen levels, may chronically stimulate the NLRP3 inflammasome." (PMID 41596350, 2026). "Experimental models fed a high-fat diet (HFD) consistently showed increased expression of NLRP3 and downstream effectors in parallel with macrophage infiltration and systemic insulin resistance, linking mitochondrial iron dysregulation to metabolic disturbances." (PMID 40943225, 2025). "In the adipose tissue, aging and metabolic dysfunction promote NOD-, LRR-, and pyrin domain-containing protein 3 (NLRP3) inflammasome activation, while targeting sirtuin 2, deacetylase regulating NLRP3, has been shown to reverse insulin resistance in aged mice." (PMID 40786636, 2025). "By interfering with NLRP3-mediated signaling at various stages—priming, activation, oligomerization, or downstream cytokine release—these compounds offer promising avenues for mitigating insulin resistance and inflammation in cardio-metabolic diseases." (PMID 40648980, 2025). "Furthermore, lower TXNIP levels directly inhibit the sparking of the NLRP3 inflammasome, an essential sensor that stimulates the production of pro-inflammatory cytokines like IL-1β that are connected to insulin resistance and β-cell mortality." (PMID 41300521, 2025). "In the state of hyperglycemia, abnormal expression of MIOX activates NLRP3 inflammasomes, leading to increased release of inflammatory mediators, promoting inflammatory response, leading to pancreatic cell damage, and exacerbating insulin resistance." (PMID 39966875, 2025). "Resveratrol may suppress the NLRP3 inflammasome through the activation of Sirt1 and Sirt6, thereby improving insulin resistance." (PMID 40433411, 2025). "These processes converge on signaling pathways such as Toll-like receptor 4/nuclear factor-κB, c-Jun n-terminal kinase, and the NOD-like receptor family pyrin domain-containing protein 3 (NLRP3) inflammasome, leading to insulin resistance, endothelial dysfunction, and atherogenesis." (PMID 41301434, 2025). "Intracellular inflammatory pathways, such as NF-kB, Janus kinases (JAK)/Signal Transducers and Activators of Transcription (STAT), and the activation of the NLRP3 inflammasome, orchestrate metaflammation, which contributes to the pathogenesis of insulin resistance, T2DM, and cardiovascular disease." (PMID 41226484, 2025). "Additionally, TXNIP is a key activator of the NLRP3 inflammasome, a complex that triggers the maturation and release of pro-inflammatory cytokines like IL-1β, which directly promote insulin resistance and β-cell damage." (PMID 41300521, 2025). "Inhibiting NLRP3 could protect against insulin resistance and myocardial fibrosis in diabetic cardiomyopathy (DCM) models." (PMID 40864768, 2025). "Accordingly, the inhibition of NLRP3 activation could provide a basis for the development of new therapeutic strategies for the treatment of insulin resistance in women with PCOS." (PMID 39268230, 2024). "Furthermore, LrB can reduce inflammation and insulin resistance in individuals with PCOS by inhibiting NLRP3, Caspase-1, TNF-α, IL-6, IL-1β, and IL-18 and increasing the expressions of GPR120, LKB1, and AMPK." (PMID 39456928, 2024). "Moreover, another member of the NOD-like receptor family, the NOD, leucine-rich-containing family, pyrin domain-containing-3 (Nlrp3), has also been identified as a stirrer-up of obesity-induced insulin resistance." (PMID 39200288, 2024). "According to these results, activation of AMPK and/or inhibition of NLRP3 activation could provide a basis for the development of new therapeutic strategies for the treatment of insulin resistance in women with PCOS." (PMID 39268230, 2024). "Insulin may contribute to immunomodulatory events by regulating the activation of the NLRP3 inflammasome in monocyte-derived macrophages, but there is also a direct link between insulin resistance and increased NLRP3 expression." (PMID 39200288, 2024).
Insulin resistance (continued). "In addition, NLRP3 interacts with protein kinase Cε (PKCε) in hepatocytes, leading to the development of hepatic insulin resistance." (PMID 39268230, 2024). "However, after weight loss in obese T2DM patients, the expressions of IL-1β and NLRP3 inflammasome are decreased, and the FBG and insulin resistance in T2DM patients are also decreased." (PMID 38725443, 2024). "Thus, the inhibition of NLRP3 inflammasome activation shows promise in preventing the progression of insulin resistance to T2DM." (PMID 39590865, 2024). "The inhibition of the TXNIP/NLRP3 inflammasome pathway by miR-17 was confirmed in β cells of diabetic rats, brains of hypoxic-ischemic injured rats, and retinal Müller glial cells of mice after induction of high fat diet-induced insulin resistance." (PMID 39220230, 2024). "Similarly, experiments have shown that rats fed a high-salt diet exhibit increased oxidative stress followed by the activation of the NLRP3 inflammasome to induce insulin resistance, while potassium supplementation improves insulin resistance." (PMID 36378463, 2023). "Thus, the results indicated that inhibiting NLRP3 inflammasome activation can attenuate insulin resistance in the 3×Tg-AD mice." (PMID 36978970, 2023). "Herein, we aimed to determine whether the NLRP3 inflammasome correlates with insulin resistance and liver pathology in a cohort of pre-diabetic subjects." (PMID 36817440, 2023). "In this study, for the first time according to our knowledge, we found that 6-month combined Yijingjing and resistance training was able to alleviate systemic insulin resistance and liver injury, and inhibit the overactivation of NLRP3 inflammasome in pre-diabetic elderly subjects." (PMID 36817440, 2023). "Moreover, positive correlations between insulin resistance, liver pathology and NLRP3 inflammasome were also found." (PMID 36817440, 2023). "Moreover, increased glucose levels also contribute to a low-chronic inflammatory state and insulin resistance partly through NLRP3 inflammasome activation and IL-1β production in subcutaneous adipose tissue (SAT)." (PMID 37819510, 2023). "The NLRP3 inflammasome may serve as a potential mechanism for the interaction between insulin resistance and ischemic cerebrovascular disease." (PMID 36950100, 2023). "Inhibiting NLRP3 inflammasome activation using CY-09, a specific inhibitor for NLRP3, may restore cerebral glucose metabolism by increasing the expression and distribution of glucose transporters and enzymes and attenuating insulin resistance in AD mice." (PMID 36978970, 2023). "Moreover, thioredoxin-interacting protein (TXNIP), a protein connected to insulin resistance, interacted with NLRP3." (PMID 37859981, 2023). "Insulin resistance and hyperglycemia can activate the NLRP3 (NOD (nucleotide oligomerization domain)-, LRR (leucine-rich repeat)-, and PYD (pyrin domain)-containing protein 3) inflammasome, leading to the release of cytokines such as interleukin-1, interleukin-6, and tumor necrosis factor-α." (PMID 37375712, 2023). "Moreover, it has been demonstrated that High Fat diet induces insulin resistance through NLRP3 inflammasome activation, and by a subsequent IL-1β secretion and ROS production in mouse AT." (PMID 37819510, 2023). "Tai Chi intervention may improve blood glucose, lipid levels, and insulin resistance in middle-aged and elderly pre-diabetic patients by reducing the level of NLRP3 inflammasome and its related inflammatory factors." (PMID 36248820, 2022). "UA can also inhibit the trigger of insulin signaling at receptor level through an ectonucleotide pyrophosphatase / phosphodiesterase 1 (ENPP1) recruitment, and induce insulin resistance by NOD-like receptor family pyrin domain containing 3(NLRP3) inflammasome activation." (PMID 36464722, 2022). "Moreover, NLRP3 expression has been also positively correlated with increased BMI, insulin-resistance and negatively correlated to adiponectin levels." (PMID 35158762, 2022).
Insulin resistance (continued). "The potential mechanism is that Tai Chi intervention could increase the level of irisin in the blood, and inhibit the expression of the NLRP3 inflammatory signal pathway, thereby reducing inflammation and relieving insulin resistance." (PMID 36248820, 2022). "Transgenic mice lacking NLRP3 fed with a high-fat diet, which has previously been shown to activate NLRP3, have lower IL-1β and are protected from high-fat diet-induced insulin resistance, further supporting inflammatory mediators’ involvement in metabolic inflammation and insulin resistance." (PMID 35754962, 2022). "The activation of NLRP3 is closely related to insulin resistance in many metabolic diseases." (PMID 35647084, 2022). "Indeed, NLRP3 and NALP3 inflammasomes mediate endothelial dysfunction, main contributors to both salt sensitivity and insulin resistance as proposed earlier." (PMID 34966295, 2021). "However, Nlrp3 knockout protected mice from the pathological effects of beta-amyloid oligomers and protected against the development of insulin resistance, which was manifested by the unchanged level of expression of IRS1-Ser compared to the control." (PMID 34769018, 2021). "Interestingly, whereas saturated fatty acid activates the NLRP3 inflammasome in mice and contributes to insulin resistance, unsaturated fatty acid attenuates IL-1β-mediated insulin resistance by preserving AMPK activity." (PMID 33546399, 2021). "In the adipose tissue of such individuals, the expression of the NLRP3 inflammasome components, the activity of caspase-1, and the level of IL-1β are increased, all of which are directly correlated with insulin resistance, metabolic syndrome, and the severity of T2DM." (PMID 33546399, 2021). "Interestingly, similar results were obtained in soleus muscle homogenates, suggesting that augmented NLRP3 protein content is a phenomenon that occurs in different types of muscles during insulin resistance." (PMID 34638553, 2021). "Together, our findings suggest that skeletal muscle could contribute to plasma IL-1β through increased NLRP3 expression in this tissue during insulin resistance." (PMID 34638553, 2021). "Moreover, the decrease of mRNA expressions of IL-1β and NLRP3 were positively correlated with the decrease of blood glucose and the improvement of insulin resistance index." (PMID 34639204, 2021). "The common end point of NLRP3 inflammasome activation is a chronic systemic inflammatory state because the locally secreted inflammatory cytokines are released into blood with subsequent development of global insulin resistance." (PMID 34966295, 2021). "These authors also reported that NLRP3 expression positively correlated with insulin resistance." (PMID 33546399, 2021). "Moreover, they show that NLRP3 deacetylation by SIRT2 regulates aging-associated inflammation and insulin resistance." (PMID 33803627, 2021). "Moreover, we also discuss the mechanisms by which the NLRP3 activation potentially links inflammation, peripheral and central insulin resistance, and metabolic changes with AD." (PMID 34070553, 2021). "In addition, due to reduced NLRP3 levels, type 2 diabetic patients have increased insulin resistance after caloric restriction and exercise." (PMID 33692776, 2020). "Furthermore, in adipose tissue, activation of NLRP3 inflammasome results in inflammation and insulin resistance." (PMID 33076522, 2020). "The mechanisms might be that elevated SUA results in insulin resistance, mitochondrial oxidative stress, endoplasmic reticulum stress, induced reactive oxygen species, and activation of the NLRP3 inflammasome." (PMID 32192511, 2020). "Therefore, it is reasonable to conclude that insulin resistance observed in Kir6.1 mice is a consequence of the overactivation of the NLRP3 inflammasome induced by Kir6.1 deletion." (PMID 31387986, 2019).